ACKR3 (atypical chemokine receptor 3)
Diseases named in the same sentence as ACKR3 in open-access papers (continued):
Sharing a sentence is not in itself a finding about the gene and the disease.
tumor (continued). "ACKR3 can also influence tumor vascularization by regulating CXCL12 levels." (PMID 29156704, 2017). "Various mechanism have been proposed by which ACKR3 may sustain tumor development including promoting tumor growth, dampening apoptosis or favoring metastasis formation." (PMID 29156704, 2017). "Also, more frequent expression of the chemokine receptor gene ACKR3 (CXCR7) which binds SDF-1 may provide tumor cell adhesion in the pre-metastatic niche." (PMID 38250718, 2024). "Hence, targeting ACKR3-mediated tumor dissemination is appealing." (PMID 36713377, 2022). "Importantly, the scavenging function of ACKR3 has also been presented as a mechanism that is notably involved in the proper positioning of neurons in the developing mouse brain or in tumour metastasis via the egress of CXCR4-expressing cancer cells from the primary tumour site." (PMID 33466410, 2021). "Additionally, ACKR3 was visualised in these tumours with an [125I] radiolabelled antibody." (PMID 33506623, 2021). "In addition, endothelial ACKR3 exerts anti-tumor actions in cancer." (PMID 33096815, 2020). "Therefore, targeting ACKR3 could prevent lymph node entry and distant metastasis of CXCR4+/ACKR3+ positive tumor cells." (PMID 30800123, 2019). "Thus, once the tumorigenesis process creates a hypoxic tumor microenvironment, ACKR3 expression by TEC may be induced by both HIF1a and VEGF." (PMID 30800123, 2019). "As chemotaxis is an important biological behavior process often used by tumor cells for metastasis and invasion CXCR4, its ligand CXCL12, and atypical receptor ACKR3 are overexpressed in many human cancers." (PMID 40427609, 2025). "The reciprocal modulation between the CXCL12/CXCR4/ACKR3 axis and the STAT3 signaling pathway plays a crucial role in the progression of various diseases and neoplasms." (PMID 38920657, 2024). "CXCL12 influences tumor progression through interactions with its 2 receptors, CXCR4 and ACKR3, especially CXCR4." (PMID 39545420, 2024). "The CXCL12/CXCR4/ACKR3 signaling axis activates the STAT3 pathway, playing a central role in tumor proliferation, metastasis, anti-apoptosis, maintenance of tumor stemness, and immune escape." (PMID 38920657, 2024). "Mechanistically, MIF independently interacts with CD74 in a hetero-complex with CD44, CXCR2, CXCR4, and ACKR3 to initiate downstream MAPK and PI3K pathways, all of which influence tumor initiation, growth, and metastatic dissemination." (PMID 38065972, 2023). "These chemokines also interact with the atypical chemokine receptors (ACKR2, ACKR3, ACKR4) expressed by both keratinocytes and fibroblasts, provoking excessive Th17 responses and amplifying skin inflammation." (PMID 37308489, 2023). "Ratio differences of important immune-related AS events (clualt3p199530 NRG1, clualt5p154454 SH3BP2, clualt5p114936 ACKR3, clualt5p152292 IL15, cluir97910 NFKBIB, and clualt5p204621 IKBKG) between tumor and normal tissues are presented." (PMID 37139238, 2023). "ACKR3 has a primary role as mediator of CXCL12 activity and has pleiotropic roles in tumor development." (PMID 36253784, 2022). "Although CXCR4 and ACKR3 can be co-expressed on tumour cells, CXCR4 tends to be more highly expressed on GSCs, whereas ACKR3 is detected at higher levels on differentiated tumour cells." (PMID 33803414, 2021). "Increased tumor cell proliferation and growth were also found to be exerted by CXCL12 and its two receptors, CXCR4 and CXCR7/ACKR3, primarily in the context of hormonal stimulation." (PMID 32582148, 2020). "Activation of ACKR3 induces VEGF expression and tumor growth but impairs invasion contrary to CXCR4." (PMID 33096815, 2020). "Whereas, CXCR7/ACKR3 has predominantly pro-metastatic roles in cancer, ACKR1 and ACKR4 demonstrate mainly tumor-restricting effects." (PMID 32582148, 2020). "ACKR3 expression is increased in GBM, especially in tumor cells and vessels, and correlate with a bad prognosis." (PMID 33066172, 2020).
tumor (continued). "Along the same lines, following EGF stimulation a CXCR7/ACKR3-mediated process of EGFR activation was revealed (possibly through β-arrestin scaffold), leading to increased tumor cell proliferation." (PMID 32582148, 2020). "Expression of S100A4, ACKR3, and CDH1 proteins in tumor samples from Doc-resistant and Doc-sensitive PCa patients was detected by western blotting and IHC." (PMID 31895690, 2019). "In lung adenocarcinoma, ACKR3 mediates TGF-ß1 promoted epithelial to mesenchymal transition (EMT) and tumor growth." (PMID 30894861, 2019). "By contrast, ACKR3 became markedly upregulated as up to 50% of the conditioned cells (ex vivo) expressed the receptor, indicating that after localized tumor passage the presence of two populations existed, namely ACKR3+/CXCR4+ and ACKR3-/CXCR4+cells." (PMID 29156704, 2017). "The observation suggests that tumor evasion and spreading of DLBCL VAL cells required ACKR3 expression." (PMID 29156704, 2017). "The silencing of ACKR3 also leads to decreased matrix metalloproteinase-2 (MMP2) and vascular endothelial growth factor (VEGF) expression, inhibiting migration and invasion of tumor endothelial cells in hepatocellular carcinoma." (PMID 38920657, 2024). "ACKR3/CXCR7 is a prominent prosurvival receptor for primary and tumor cells alike." (PMID 35053329, 2022). "For ACKR3, ERK and AKT activation has been shown to be essential in promoting cancer cell survival, proliferation and tumor angiogenesis, whilst the biological relevance for ACKR2 is still unknown." (PMID 36483536, 2022). "ACKR3 (previously termed the RDC1 orphan receptor or C-X-C chemokine receptor type 7 (CXCR7)) is a 7 transmembrane receptor expressed on various cell types, including hematopoietic, vascular, and tumor cells." (PMID 35383158, 2022). "CXCR4 and ACKR3 were found upregulated in tumor core GBM cells (without distinction of necrotic and/or angiogenic features) compared to infiltrating area and healthy tissue, which is supportive of the IvyGAP data." (PMID 35008294, 2021). "Thus, CXCL12 prevents tumour cell apoptosis following camptothecin or TMZ treatment, but drug sensitivity can be re-established in the presence of the ACKR3 antagonist CCX733." (PMID 33803414, 2021). "In fact, CXCR4, SPP1, ACKR3, CCL2, PTGS2, CD274 (PD-L1), CXCL11 were upregulated while CCL28, CCR1, CCR7 were down regulated in both comparisons (blue boxes), suggesting this as a signature specific of the core region of the tumor." (PMID 33066172, 2020). "Aside from controlling motility-related aspects in cancer, such as tumor cell invasion, endothelial cell migration (angiogenesis) and eventually tumor progression in vivo, CXCR7/ACKR3 regulates non-conventional cancer-related activities." (PMID 32582148, 2020). "The described controversial roles of ACKR3 in tumor formation and metastasis do not allow making general predictions." (PMID 29156704, 2017). "However, subsequent to the confirmation of ACKR3 as a receptor of CXCL12, a plethora of studies have verified that the binding of CXCL12 and ACKR3 can also activate the STAT3 pathway, thereby fostering tumor development." (PMID 38920657, 2024). "However, no study has elucidated the specific molecular mechanisms by which the CXCL12/CXCR4/ACKR3 axis activates the JAK2/STAT3 pathway, and responses to the CXCL12/STAT3 signal transduction may vary across different tumor types and cell lines." (PMID 38920657, 2024). "These genes, including ERBB2, CCNA1, FOXC2, LEFTY2, VTN, ACKR3, and PTGS2, are involved in key processes like apoptosis, epithelial–mesenchymal transition, angiogenesis, response to hypoxia, and KRAS signaling pathways, which are crucial for tumor virulence and the spread of metastases." (PMID 39000413, 2024).
tumor (continued). "Among these genes are ERBB2, CCNA1, FOXC2, LEFTY2, VTN, ACKR3, and PTGS2, which influence processes such as apoptosis, epithelial–mesenchymal transition, angiogenesis, hypoxia responses, and KRAS signaling pathways, all vital for tumor aggressiveness and metastatic spread." (PMID 39000413, 2024). "On the contrary, no role could be identified for ACKR3 in promoting proliferation, survival or migration of tumour cells." (PMID 33803414, 2021). "Additionally, it was revealed that in breast and prostate cancers ACKR3 may form heterodimers of another type, with epidermal growth factor receptor (EGFR), what contributes to promoting tumor cell proliferation in these malignancies." (PMID 32456359, 2020). "However, it was demonstrated that ACKR3, by forming heterodimers with CXCR4 and modifying CXCR4 signaling, may also promote tumor growth and/or metastasis." (PMID 32456359, 2020). "The tumor-restricting activities of CXCR7/ACKR3 may be connected to the fact that unlike CXCR4, it is an atypical chemokine receptor (and thus was given the additional name ACKR3)." (PMID 32582148, 2020). "In addition, ACKR3, formerly known as CXCR7, is a scavenger receptor for CXCL11 that may reduce the availability of CXCL11 in vivo and in the tumor bed." (PMID 31216755, 2019). "We focus on ACKR1 (DARC), ACKR3 (CXCR7), CXCR4, and CCR2, as these are the best studied chemokine receptors in TEC; and suggest that targeting these receptors on the tumor vasculature may prove efficacious in slowing or reversing tumor growth." (PMID 30800123, 2019). "In the present study ACKR3 was genetically deleted on the tumor cells while the receptors expressed on mouse tissue were not inhibited, suggesting that expression of ACKR3 on VAL cells was required for spreading via lymphatics but was independent of elevated CXCL12 levels." (PMID 29156704, 2017). "The tumor-derived EVs did not carry CXCR4 nor ACKR3 protein, suggesting the transfer of other molecules that induce ACKR3 expression." (PMID 39698539, 2024). "Inspection of the data of De Kegel and Ryan, 2019 shows that ACKR3, CX3CR1, TBXA2R were not assigned to the essential category in any of the 558 tumor cell lines tested." (PMID 33427197, 2021). "A study using selective ACKR3 modulators emphasized the involvement of ACKR3 in GSC growth in vitro together with CXCR4, although this report revealed that GSC tumor formation in vivo was independent of CXCR4 or ACKR3 activity." (PMID 35008294, 2021). "Like CXCR7—known also as ACKR3—other ACKRs do not transmit intracellular signals through heterotrimeric G proteins, and regulate many aspects of tumor progression." (PMID 32582148, 2020). "CXCL12 is expressed by microvascular endothelial cells and stimulated proliferation of GBM progenitor cells but not differentiated tumor cells via CXCR4, whereas ACKR3 was not involved." (PMID 30813533, 2019). "Furthermore, we have seen that ACKR3 can induce ERK and Akt phosphorylation in a different kinetic and spatial sequence to CXCR4 and alter receptor internalization and thus may still be involved in other pathways such as NF-κB-mediated survival, tumour growth and angiogenesis." (PMID 30441765, 2018). "The atypical chemokine receptor 3 (ACKR3), which does not couple to G-proteins and does not mediate cell migration, acts as a scavenger for CXCL11 and CXCL12, interfering with the tumor homing CXCL12/CXCR4 axis." (PMID 29156704, 2017).
cancer (228 papers, 2008 to 2025). A tumor composed of atypical neoplastic, often pleomorphic cells that invade other tissues. "The effects of VUN700 and VUN701 on the basal motility of HeLa and MDA-MB-231 cancer cells suggest that the constitutive activity of ACKR3 is implicated in migratory signaling." (PMID 41330916, 2025). "While ACKR3 provides a cardioprotective role, its overexpression is associated with neurodegeneration in the central nervous system and poor cancer prognosis." (PMID 41330916, 2025). "Upregulated genes in fibroblasts by High dose PBDE exposure included Sepp1, Nptn, and Ackr3, which have also been associated with cancer development and progression." (PMID 39017946, 2024). "We also demonstrated that CXCR4 and, to a greater extent, ACKR3, promote the glucose metabolism through glycolysis and the pentose phosphate pathway, processes associated with the proliferation of cancer cells." (PMID 35681470, 2022). "Higher expression of ACKR3 is also associated with poorer outcomes in terms of disease-free survival, and there is a positive correlation between high ACKR3 levels and cancer cell metastasis." (PMID 31895690, 2019). "In contrast, ACKR3 expression together with CXCR4 is associated with cancer promoting effects." (PMID 41258098, 2025). "Inhibition of basal ACKR3 activity attenuated basal cell motility, which reveals a distinct role for ACKR3 in cellular biology and cancer in particular." (PMID 41330916, 2025). "In summary, we have identified a basal state of ACKR3 that displays constitutive activity and is involved in cancer cell motility." (PMID 41330916, 2025). "Despite ACKR3’s evident role in cancer development, the specific downstream signaling pathways modulated by this receptor are still unclear." (PMID 41330916, 2025). "Accordingly, small molecule ACKR3 agonists have been widely used to probe its scavenging function, showing efficacy in various cancer models, whereas inhibition of ACKR3 activity remains underexplored." (PMID 41317408, 2025). "These receptors, such as ACKR3, CXCR4, CXCR3, play a crucial role in the regulation of the immune system, are associated with inflammatory diseases and cancer, and are seen as promising drug targets." (PMID 38732237, 2024). "Atypical Chemokine Receptor 3 (ACKR3) is a seven transmembrane domain receptor belonging to class A G‐protein‐coupled receptors and is overexpressed in numerous cancer types, including LC, and is closely associated with poor prognosis." (PMID 37496297, 2023). "ACKR3 is described as expressed on hematopoietic cells, neurons, mesenchymal cells, endothelial cells, and cancer cells, CD4 T lymphocytes, NK cells, dendritic cells, neutrophils, monocytes, and macrophages." (PMID 36552863, 2022). "Over 90% of publications concerning ACKR3/CXCR7 enlisted in PubMed stem from research in the context of various cancers, where ACKR3/CXCR7 has been shown to play a decisive role in cancer progression, angiogenesis and even prognostic outcome." (PMID 35053329, 2022). "In response to CXCL12, CXCR4 and ACKR3 both recruit β-arrestin 2, regulating the assembly of interacting proteins that drive signaling and contribute to the functions of both receptors in cancer and multiple other diseases." (PMID 35681470, 2022). "In summary, our work establishes that CXCL12 signaling controls PKM2, a central regulator of metabolism in proliferating cells, and highlights the effects of CXCR4 and ACKR3 on metabolic reprogramming in cancer." (PMID 35681470, 2022). "Luciferase complementation data showing the CXCL12-dependent dissociation of PKM2 oligomers suggested that CXCR4 and ACKR3 signaling shifted cancer cells toward glycolysis." (PMID 35681470, 2022). "Previous studies disclosed the role of ACKR3 in cell adhesion via in vitro functional assays using endothelial progenitor cells as well as cancer cells." (PMID 35674847, 2022).
cancer (continued). "Metabolism reprogramming represents another hallmark of cancer, but few studies have investigated the potential effects of CXCL12 signaling through CXCR4 or ACKR3 on metabolic shifts in cancer cells." (PMID 35681470, 2022). "Of note, the CXCL12-binding receptor Ackr3 (encoding CXCR7), which is known to form heterodimers with CXCR4 and is dysregulated in inflammatory diseases and cancers, was upregulated." (PMID 34363012, 2021). "Chemokine CXC receptor 7 (CXCR7), recently termed ACKR3, is amongst the G-protein-coupled cell surface receptor family that is commonly expressed in a large variety of cancer cells." (PMID 34298991, 2021). "Accumulating evidence indicates the involvement of ACKR3 in pathological processes, specifically in certain types of cancers and cardiovascular diseases." (PMID 33799570, 2021). "The two receptors of CXCL12, CXC receptor 4 (CXCR4) and atypical chemokine receptor 3 (AKRC3, also known as CXCR7), are expressed on PDAC cells, and an elevated expression of CXCR4 is associated with a poor prognosis in several cancer types." (PMID 35008248, 2021). "ACKR3-Venus animals allow for the direct observation of receptors in vivo without the need for immunodetection and will therefore be a unique tool to probe open questions about ACKR3 function in neuroscience, cardiovascular system, and cancer." (PMID 34583741, 2021). "With considerable drug development efforts underway for anti-cancer ACKR3 therapeutics and the potential to target other disorders, including brain diseases there is the need for improved tools to study ACKR3 ex vivo and in vivo." (PMID 34583741, 2021). "According to the literature, ACKR3 has been reported to be co-expressed with CXCR4 to modulate CXCR4 signalling in cancer cells." (PMID 34060588, 2021). "At present, ACKR3 is considered a target for cancer and cardiovascular disorders, but less is known about the potential of ACKR3 as a target for brain disease." (PMID 34583741, 2021). "The array of atypical cancer-regulating functions of CXCR7/ACKR3—when it acted alone or in the context of CXCR4—were discussed in the previous sections of the article, as appropriate." (PMID 32582148, 2020). "CXCR7, a member of the subgroup of atypical chemokine receptors (ACKRs) known also as ACKR3, opens the gate for discussion of atypical activities of additional ACKRs in cancer: ACKR1 (DARC, Duffy), ACKR2 (D6), and ACKR4 (CCRL1)." (PMID 32582148, 2020). "So far, one radiolabeled highly selective antibody (ACKR3-mAb) has been tested for in vivo assessment of CXCR7 in mice xenografted with human cancer cells showing correlation of tracer uptake with CXCR7 immunoreactivity." (PMID 33281749, 2020). "In contrast to other atypical receptors of chemokines, ACKR3 expression by cancer cells promotes the tumorigenesis process in most cases." (PMID 32456359, 2020). "CXCL8 also upregulates CXCR7/ACKR3, which is involved in stemness features of cancer cells suggesting it is also likely involved in EPC mobilization." (PMID 30800123, 2019). "A second receptor for CXCL12, the CXCR7/ACKR3 protein is upregulated in cancer and is also believed to contribute to metastasis." (PMID 31027259, 2019). "But following fetal development and birth, expression of ACKR3 protein is difficult to detect on the surface of cells or tissues, except in the context of cancer." (PMID 30800123, 2019). "ACKR3 is upregulated in many different cancer types including lung, cervical, pancreatic, myeloid, glial, and prostate cancer cells and brain cancer." (PMID 30800123, 2019). "ACKR3 generally is not considered a chemotactic receptor, however, addition of CXCL12 enhances ACKR3+/CXCR4+ cancer cell migration across endothelial cells toward CCL19 and CXCL13, chemokines expressed by endothelial cells inside the lymph nodes." (PMID 30800123, 2019). "The CXCL12/CXCR4/ACKR3 axis is frequently hijacked by cancer cells to promote their survival, growth, resistance to chemotherapy, metastasis and immune evasion." (PMID 30257500, 2018).